ITGB4 (integrin subunit beta 4)
Diseases named in the same sentence as ITGB4 in open-access papers (continued):
Sharing a sentence is not in itself a finding about the gene and the disease.
viral infection (1 paper, 2024). "The continued downregulation of structural genes like ITGB4 and metabolic genes like EEF2 across different viruses could reflect a sustained reprogramming of cellular processes in the extended phase of viral infection." (PMID 38655085, 2024).
tumor (152 papers, 2006 to 2026). "While research has confirmed the differential expression of upstream and downstream molecular pathways associated with ITGB4, a significant knowledge gap remains regarding its role in tumor biology, particularly its function as a cell adhesion molecule." (PMID 39169946, 2024). "Our analysis of single-cell sequencing data showed that ITGB4 is highly expressed on tumor associated fibroblasts." (PMID 38172503, 2024). "The ITGB4 (Integrin subunit beta 4) gene encodes a receptor for laminins and its upregulation in tumor tissues is associated with poor prognosis." (PMID 38172503, 2024). "Clinical material also shows an inverse correlation between ITGB4 expression and number of tumor-associated leukocytes." (PMID 36932441, 2023). "ITGB4+PD-L1+ tumor cells were found to be significantly associated with CD8+ T cells (positivity p = 0.005, positive number p = 0.03)." (PMID 37371594, 2023). "Most pronounced, however, was the super-additively delayed tumor growth in the presence of concomitant ITGB4 KD and E-/P-selectin double deficiency, whereas E-/P-selectin deficiency alone had no such effect on tumor growth." (PMID 36932441, 2023). "Intriguingly, we observed a highly significant inverse association of ITGB4 and the level of tumor-associated CD45+ leukocytes (p < 0.001)." (PMID 36932441, 2023). "In the frame of EGFR-mediated EMT, ITGB4 was identified as a mechanistic biomarker that is essential for local invasion, is associated with tumor budding, is a target for antagonizing antibodies, and represents a novel predictive marker candidate." (PMID 36076232, 2022). "Edge localization of ITGB4 was observed in 31.1% of cases (33/106) and was associated with significantly more tumor budding and higher budding intensity than the homogeneous ITGB4 localization." (PMID 36076232, 2022). "In vivo, preferential ITGB4 expression in peripheral cells of tumor areas was significantly associated with a higher degree of tumor budding, which is a hallmark of local invasion and metastasis formation associated with reduced OS." (PMID 36076232, 2022). "Integrin β4 (ITGB4) is a tumor-associated antigen, which is highly expressed in a variety of malignant tumors and plays a role in promoting tumor metastasis." (PMID 36203272, 2022). "A survey of scRNA-seq datasets from n = 28 different cancer entities further demonstrated that ITGB4 showed the strongest and most strongly tumor-associated expression in HNSCC compared to all other tumors." (PMID 36076232, 2022). "ECAD, ITGB4, and ZO‐1 were inversely associated with tumor stage, while cytokeratins showed a positive association." (PMID 34890102, 2022). "That is, PD-L1 promotes tumor growth and metastasis via ITGB4/SNAI1/SIRT3 signaling, and this is one of the main causes of PD-L1 resistance." (PMID 32000802, 2020). "High ITGB4 expression was observed to be associated with elder onset age, proximal tumor location, and high microsatellite instability (MSH) status." (PMID 31602273, 2019). "In integrated analyses, high ITGB4 expression was associated with elder onset age, proximal tumor location, and MSH status." (PMID 31602273, 2019). "As ITGB4 is associated with promoting the invasion and metastasis of tumor cells in several cancers, in the present study, we examined the role if ITGB4 in HCC in vitro and in vivo and explored the underlying mechanisms." (PMID 28084395, 2017). "Integrin β4 (ITGB4), which facilitates the bidirectional exchange of information between intracellular and extracellular matrices, has been implicated as a key regulator of tumor migration and invasion and was upregulated in A20 KO cells." (PMID 40072109, 2025). "This is consistent with findings from numerous studies showing that the TME is closely associated with tumor related immunity and indicates that ITGB4 may contribute to poor LGG prognosis via its effects on tumor immune responses." (PMID 38172503, 2024).
tumor (continued). "Filtering and standardizing the single-cell sequencing data revealed that ITGB4 is highly expressed in tumor-associated fibroblasts, indicating that ITGB4 may regulate the function of fibroblasts in the TME." (PMID 38172503, 2024). "ITGB4 is a well-characterized signaling molecule linked to tumor cell migration and invasion." (PMID 39169946, 2024). "Numerous studies have implicated ITGB4 as a key facilitator of tumor migration and invasion." (PMID 39169946, 2024). "ITGB4, a member of the integrin family, has been implicated in tumor progression." (PMID 38172503, 2024). "Moreover, the ITGB4 level was inversely associated with the presence of tumor-associated CD45+ leukocytes." (PMID 36932441, 2023). "Additionally, ITGB4 has been linked to the clinicopathological characteristics of cancer, such as tumor stage and pathological grade." (PMID 37371594, 2023). "Considering the number of tumor-associated leukocytes based on anti-hCD45 stainings on consecutive slides of primary, locally advanced and distant metastasis samples revealed a highly significant inverse association with the ITGB4 level." (PMID 36932441, 2023). "With ITGB4 overexpression found across several cancer types, and its association as an adverse prognostic marker, ITGB4-focused therapies represent a potential therapeutic approach to direct host immune responses against both CSCs and bulk tumor cells." (PMID 34504657, 2021). "We found ITGA3 significantly associated with primary therapy outcome (p < 0.0001), ITGA6 significantly associated with OS status (p = 0.026), ITGB4 significantly associated with cancer status (p = 0.042) and tumor residual (p = 0.024), ITGB8 significantly associated with chemotherapy (p = 0.020)." (PMID 32765584, 2020). "Moreover, the significantly upregulated DEPs (ITGA1, ITGA6, and ITGB4) that were associated with tumor invasiveness and aggressiveness were confirmed by immunoaffinity analysis in FSH-positive vs. negative NFPAs." (PMID 31832114, 2019). "Apparently, E-/P-selectin deficiency in the tumor stroma creates a previously unknown vulnerability of TCs to additional ITGB4 depletion, which was also suggested by increased ITGB4 expression in the xenograft tumors in E-/P-selectin KO mice in several of the tested models." (PMID 36932441, 2023). "We then validated the inhibitory effect of these combinations by performing western blot on tumor tissues and cultured cells treated with the same conditions as in vivo experiment and identified the similar reduction of ITGB4 and COL1A1." (PMID 40386428, 2025). "This subtype exhibited enhanced basal‐like and stemness features and showed high LAMC2 expression, which activated laminin‐integrin signaling via ITGA6/ITGB4, promoting tumor invasiveness." (PMID 40470730, 2025). "Further examination of the DEPs revealed that several signaling molecules previously identified at the tumor boundary, including ITGB4, COL1A2, and VIM, were significantly upregulated in the cancer-adjacent tissue (p.adjust < 0.05)." (PMID 40725477, 2025). "Integrin beta 4 (ITGB4) forms a critical link between the extracellular matrix and the cell interior by interacting with focal adhesion via paxillin, and its presence in tumor-derived exosomes facilitates the creation of a microenvironment that promotes LC." (PMID 41440381, 2025). "ITGB4 overexpression has been demonstrated in HNSCC, and recently, in a mouse model, ITGB4 immunotherapy was successfully used to reduce tumor growth and metastasis." (PMID 40287842, 2025). "Overexpression of ITGB4 shows significant correlations with tumor development and metastasis in several cancers including PDAC." (PMID 40386428, 2025). "The association with extracellular vesicles would be the most plausible explanation, as high tumor ITGB4–UEA expression was related to distant metastasis." (PMID 40287842, 2025).
tumor (continued). "Overall, the luminal-associated transcriptional programs (FOXA1-EHF-ITGB4) and its downstream ECM-receptor interaction pathway (SPP1, CD44, ITGB4) play a crucial role in IMA, influencing its immunity and tumor risk." (PMID 39584073, 2025). "To conform this, we performed a western blot from the tumor tissues and found that combination treatment significantly inhibits the expression of ITGB4." (PMID 40386428, 2025). "Vaccines based on ITGB4-expressing dendritic cells (mITGB4-DC) or adoptive transfer of BiAb-armed T cells targeting ITGB4 have been shown to suppress both CSCs and bulk tumor cells in preclinical models, reducing local tumor growth and metastasis." (PMID 41439922, 2025). "Significantly, while the ITGB4–UEA assay resulted in the highest S/B ratio in UT‐SCC cell lysates and in serum samples from HNSCC patients, the S/B ratios of the ITGB4–UEA assay were among the lowest in tumor and normal adjacent tissues." (PMID 40287842, 2025). "Meanwhile, hypomethylation of several oncogenes such as NRG1, ITGB4 and GALNT6 associated with tumor-enriched bacteria suggests the potential of microbiota to promote host gene expression through epigenetic activation." (PMID 38589501, 2024). "In a recent study by Genduso and colleagues, they investigated how the interplay between integrin β4 (ITGB4) on tumor cells and E-/P-selectin on endothelial cells in the tumor stroma impacts the regulation of tumor growth and influences the immune environment." (PMID 39432076, 2024). "The most pronounced differences in the frequencies of tumor progression-related gene expression were observed in the CTCs expressing ITGB4 with complementary ITGA6 (group 8)." (PMID 38250718, 2024). "In summary, the multifaceted influence of ITGB4 on a diverse array of downstream signaling molecules underscores its critical role in promoting tumor migration and invasion across a spectrum of cancers." (PMID 39169946, 2024). "This review provides a foundational description of the mechanisms by which ITGB4 regulates tumor migration and invasion through pathways involving focal adhesion kinase (FAK), protein kinase B (AKT), and matrix metalloproteinases (MMPs)." (PMID 39169946, 2024). "We aimed to elucidate how ITGB4 interacts with these factors to influence tumor migration and invasion." (PMID 39169946, 2024). "ITGB4 promotes tumor progression by amplifying distinct signaling pathways and facilitating tumor cell migration and invasion." (PMID 39169946, 2024). "Further studies are warranted to elucidate the precise molecular mechanisms by which ITGB4, a critical molecule in tumor progression and a potential target for therapeutic intervention, contributes to tumor development and metastasis." (PMID 39169946, 2024). "The analysis of clinical samples supported these findings, indicating an inverse relationship between the expression of ITGB4 in tumors and the number of leukocytes infiltrating the tumor." (PMID 39432076, 2024). "Collectively, these findings highlight the strong correlation between ITGB4 expression and tumor cell migration and invasion." (PMID 39169946, 2024). "Several studies have shown that ITGB4 influences the migration and invasion of tumor cells through the activation of FAK." (PMID 39456433, 2024). "Integrin β4 (ITGB4, also known as CD104), a member of the tryptophan-aspartic acid (WD)-40 repeat family, is a tumor-associated antigen (TAA) exhibiting high expression levels in diverse malignant tumors." (PMID 39169946, 2024). "Increased ITGB4 expression is involved with tumor growth, progression, and metastasis in CRC, and unfavorable overall survival." (PMID 38992681, 2024). "The multifaceted role of ITGB4 in tumor migration and invasion is further highlighted by its diverse effects across different cancer types." (PMID 39169946, 2024).
tumor (continued). "In the next step, we aimed to validate our most striking observation, i.e., the synergistic and almost complete reduction of xenograft tumor formation upon combined ITGB4 KD and E-/P-selectin KO by means of additional ITGB4-expressing xenograft models." (PMID 36932441, 2023). "This study shows that depletion of ITGB4 in TCs of several tumor entities in different model systems leads to a delay in tumor growth." (PMID 36932441, 2023). "ITGB4 was upregulated in various tumor types and was linked to poor prognosis or aggressive behavior." (PMID 37214471, 2023). "In PC-3 tumor nodules harvested on day 8 after injection, the enhanced leukocyte infiltrate in ITGB4 KD tumors was again visible, characterized by arginase-1- and myeloperoxidase (MPO)-positive cells." (PMID 36932441, 2023). "More interestingly, when the relationship between ITGB4+PD-L1+ tumor cells and CD8+PD-1+ T cells was analyzed, their correlation was found to be statistically different (positivity p = 0.02, positive number p = 0.03)." (PMID 37371594, 2023). "Increased attraction of CD11b+ Gr-1Hi SSCLo cells (e.g., MDSCs) appears to be of particular importance for the establishment of ITGB4 KD xenografts and requires endothelial selectins of tumor vessels for infiltration." (PMID 36932441, 2023). "ITGB4 staining occurred in the tumor cells (mostly in the invasion frontier) and the basal layer of the normal oral mucosa." (PMID 37371594, 2023). "ITGB4-depleted tumors undergo apoptosis and actively attract MDSCs, well-known to promote tumor growth in several cancers, via increased secretion of different chemokines." (PMID 36932441, 2023). "Again, the combination of ITGB4 KD and E-/P-selectin KO most strikingly reduced tumor formation: only two out of nine mice developed tumors after 186.4 ± 26.9 days." (PMID 36932441, 2023). "The mIHC staining results show that ITGB4 was mostly expressed in the tumor cells, with a significant increase in the OSCC specimens compared with normal oral epithelium and oral epithelium dysplasia." (PMID 37371594, 2023). "In this study, we analyzed the cooperative effects of integrin β4 (ITGB4) on tumor cells and E-/P-selectin on endothelial cells within the tumor stroma for regulating tumor growth by shaping the local and systemic immune environment." (PMID 36932441, 2023). "ITGB4 expression was examined at the protein level from tumor lysates and normalized to GAPDH levels as detected by WB analyses." (PMID 36932441, 2023). "Our recent work showed that NSCLC tumor tissue has the heterogenous expression of PXN/ITGB4, and patients with the increased expression of both these genes have poor overall survival." (PMID 36675528, 2023). "Analyses of clinical samples confirmed an inverse relationship between ITGB4 expression in tumors and number of tumor-infiltrating leukocytes." (PMID 36932441, 2023). "Others have identified Notch3 as responsible for maintenance of CD24+, ITGB4+ tumor-propagating cells in a Kras model highlighting the possibility that Notch activation is required for this phenotype across models." (PMID 37882674, 2023). "The fluorescence of Opal 520 (green) indicated the population of ITGB4+ cells, which was predominantly expressed in tumor cells." (PMID 37371594, 2023). "More importantly, ITGB4 knockdown further decreased tumor volume when mice were treated with EPI and BMN." (PMID 37787041, 2023). "The correlation between subgroups of tumor cells, including ITGB4+PD-L1+ and ITGB4+ALDH1+, and subgroups of T cells, including CD8+ and CD8+PD-1+, was evaluated using two-tailed Pearson’s statistics." (PMID 37371594, 2023). "The synergism between ITGB4 KD and selectin KO on tumor growth was observed only in the presence of double deficiency of both E- and P-selectin, but not in the presence of single deficiency of either selectin." (PMID 36932441, 2023).
tumor (continued). "Further analyses revealed that the enhanced leukocyte infiltrate of ITGB4 KD tumor nodules was characterized by arginase-1- and myeloperoxidase-positive cells." (PMID 36932441, 2023). "Later, the same synergism between ITGB4 and E-/P-selectin on tumor growth was evident in a syngeneic model in fully immunocompetent hosts." (PMID 36932441, 2023). "The number of CD8+ T cells was significantly increased at the tumor margin only after combined depletion of ITGB4 and E-/P-selectin." (PMID 36932441, 2023). "Furthermore, E-/P-selectin KO mice with ITGB4 KD tumors showed an astonishing disruption of splenic morphology (almost complete loss of follicular structures) accompanied by a decrease in splenic CD11c+ cells (presumably dendritic cells, DCs), which were concomitantly increased in the tumor nodules." (PMID 36932441, 2023). "Given the close relationship between ITGB4/PD-L1 tumor cells and CD8/PD-1 T cells, the patients were divided into four subgroups based on the expression of these cells." (PMID 37371594, 2023). "The specificity of the tumor-promoting effect of these tumor-infiltrating innate immune cells on ITGB4 KD tumors was evident as the growth of control tumors was not affected by E-/P-selectin deficiency." (PMID 36932441, 2023). "Most strikingly, however, tumor formation was almost entirely abolished after combining the ITGB4 KD with the E-/P-selectin KO." (PMID 36932441, 2023). "Briefly, a physiological state means that the expression of ITGB4 was confined to the basal layer of neoplastic cells adjacent to the tumor stroma." (PMID 37371594, 2023). "Preferential localization of ITGB4 together with its ligand laminin 5 at tumor-stroma interfaces correlated with increased tumor budding in primary HNSCC tissue sections." (PMID 36076232, 2022). "Alternatively, one study has reported that exogenous EGF can stimulate the expression of NTN4, a regulator of GBM tumor progression/proliferation via ITGB4-Akt signal activation." (PMID 36316307, 2022). "ITGB4 expression was represented in violin plots for the three tumor entities with highest expression, i.e. HNSCC, PAAD, and CRC, confirming the strong and most selective expression in malignant HNSCC cells." (PMID 36076232, 2022). "Seven ECMGs (i.e. LAMB3, LAMA3, ITGB6, ITGB4, ITGA2, LAMC2, and COL11A1) were identified to be hub genes of PAAD, which were obviously up-regulated in PAAD and considerably linked to tumor stage as well as prognosis." (PMID 36311789, 2022). "Here, laminin 5 acts as a structural ligand that generates a scaffold for the binding of ITGB4, thereby leading the way for tumor migration and invasion." (PMID 36076232, 2022). "Though not highly expressed by the other fibroblasts, spatial data revealed the presence of ITGB4 in some tumor or stromal regions." (PMID 35986392, 2022). "Matched pairs of normal mucosa and HNSCC from the TCGA-HNSCC cohort confirmed a significant over-expression of ITGB4 mRNA in tumor samples." (PMID 36076232, 2022). "As proof-of-concept for this therapeutic approach, antagonizing ITGB4 ́s interaction with laminin 5 with the ASC8 antibody strongly reduced tumor cell invasion, confirming the potential of ITGB4 as therapeutic target to block local invasion." (PMID 36076232, 2022). "Detected to overexpress in metastatic cell lines of mouse lung carcinoma and melanoma, ITGB4 was originally considered a “tumor-specific” protein, which brought about worldwide interest." (PMID 35305660, 2022). "In tumor progression however, ITGB4 and laminin 5 are involved in local invasion, thus fostering tumor cell dissemination and the generation of a minimal residual disease composed of occult tumor cells that escape classical imaging technologies." (PMID 36076232, 2022). "In this study, ITGB4 was expressed in tumor protrusions and in detached tumor buds, further supporting a possibility of targeting ITGB4 to impede early steps of local invasion and metastasis formation." (PMID 36076232, 2022).